MEIS1 (Meis homeobox 1)
Diseases named in the same sentence as MEIS1 in open-access papers (continued):
Sharing a sentence is not in itself a finding about the gene and the disease.
cancer (continued). "MEIS family genes can promote or inhibit cancer probably through the different degrees of immune silencing and the significant correlation of MEIS1 with immune genes according to a gene regulatory network analysis." (PMID 36661515, 2023). "MEIS1 expression was negatively related to tumor mutational burden (TMB), microsatellite instability (MSI) and neoantigen (NEO) in several cancers." (PMID 36836180, 2023). "Our findings showed that MEIS1 expression was strongly related to most immune cells in various types of cancer." (PMID 36836180, 2023). "Various online tools were used to analyze the data from TCGA, GTEx and GEO databases, which intended to explore the potential mechanisms of MEIS1 across different cancers." (PMID 36836180, 2023). "Another major finding is that MEIS1 expression correlates with survival in cancer patients, which indicated that the abnormal expression of MEIS1 can be responsible for the poor prognosis of tumors." (PMID 36836180, 2023). "As an important transcription factor, if MEIS1 is over-expressed or low-expressed, transcriptional misregulation will emerge and then play a role in cancer development." (PMID 36836180, 2023). "Due to its role in cancer cell proliferation, MEIS1 can become a molecular biomarker for cancer diagnosis and even a target for cancer therapy." (PMID 36836180, 2023). "The expression of MEIS1 was influenced by cell types, age, the environment humans stay in, their pathological state, and the metabolism features of cancer cells." (PMID 36836180, 2023). "Next, for determining which member contributed to the generally impaired expression of MEIS subfamily in cancers, we investigated the expression of MEIS1, MEIS2, and MEIS3 in multiple TCGA cancers." (PMID 35351858, 2022). "To confirm the potential relevance of MEIS1 to cancer stemness, we examined the protein level of MEIS1 in CSC-enriched spheres." (PMID 34948208, 2021). "We, thus, interrogated gene expression data of pre-leukemic (overexpressing Hoxa9) and leukemogenic (overexpressing Hoxa9 and Meis1; H9M) murine cell lines to identify cancer vulnerabilities." (PMID 34502319, 2021). "Our finding of a potential link between MEIS1 and the mesenchymal phenotype supports the conclusions in our manuscript that MEIS1 promotes cancer stemness and metastasis." (PMID 34948208, 2021). "The downregulated projected network had 62 known regulatory interactions, of which transcription factors TAL1, ZEB1 and MEIS1 regulate the genes which were differentially regulated in more than half of the cancers studied." (PMID 34728699, 2021). "The HOX9-11, PBX3 and MEIS1 were also involved in the ‘Transcriptional misregulation in cancer’ pathway (KEGG database), and ‘Activation of HOX genes during differentiation’ pathway (Reactome database)." (PMID 34051812, 2021). "This correlation indicates a contribution of MEIS1/SALL4 expression in operating cancer aggressiveness in ESCC." (PMID 32819319, 2020). "According to the GEPIA and BioGPS datasets, the expression of Meis1, Meis2, and Meis3 vary in different cancers." (PMID 33402862, 2020). "Meis1 has been shown to be over expressed in a number of cancers and been indicated with its oncogenic potential." (PMID 32409701, 2020). "The Meis2 expression pattern in cancer tissues differs from that of Meis1, and it also differs in adult tissues." (PMID 33402862, 2020). "Further, our findings are supported by previous reports of MEIS1 slowing growth of cancer cells through a G1 cell cycle blockade and reduced migration." (PMID 32553107, 2020). "Several genetic variants had high mutation rates across the entire study group in comparison with normal ovarian controls, e.g. recurrent deleterious variants in the CHD1L, GFM1, MEIS1 and NFX1 genes, suggesting specificity to cancer." (PMID 30416686, 2018). "As a transcription factor, HOXC8 is able to regulate and coordinate multiplevital genes (e.g. Mgl1, Embigin, Meis1, and Fyn) involved in cancer development and progression." (PMID 32922885, 2018).
cancer (continued). "In these cancers, MEIS1 would function via inhibiting cell proliferation and inducing cell cycle arrest." (PMID 28270206, 2017). "Based on the previous discovery of MEIS1, to further reveal its function and develop potential therapy in human cancer treatment are accessible." (PMID 28270206, 2017). "Although multiple roles of MEIS1 in cancer development and progression have been identified, there is an urgent demand to discover more functions of this molecule for further therapeutic design." (PMID 28270206, 2017). "In P19 and F9 carcinoma cells and in the U937 human leukemic monocyte lymphoma cell line, RA treatment rapidly induces Meis1 expression." (PMID 26857994, 2016). "In this paper we have used a set of five isogenic MEF cell lines expressing different amounts of Meis1 and/or Prep1 to understand how the increased intracellular concentration of Meis1 or Prep1 leads to or inhibits cancer, respectively." (PMID 26259236, 2015). "To identify a cancer-related Meis1 signature in M and MP cells, we subtracted from these sets the targets in common between M and WT (n = 111) and between MP and WT (n = 116)." (PMID 26259236, 2015). "The overlap of ChIP-seq and RNA-seq data has allowed to extract from the totality of their target genes a cancer-specific Meis1 and Prep1 signature." (PMID 26259236, 2015). "Since the expression of Prep1 and Meis1 is heavily affected in a very large percent of human cancers, the present data are of general pertinence and interest." (PMID 26259236, 2015). "Previous study of EIS1 fate in other cancers indicated that either MEIS1 promoter methylation, or truncated form of MEIS1, was associated with decreased MEIS1 gene expression in HNSCC." (PMID 25186767, 2014). "To investigate the effect of Meis1 deletion on carcinoma development, we monitored 32 chemically treated K14CreER-Meis1fl/fl mice and 43 chemically treated Meis1fl/fl mice up to 35 weeks after tumor initiation." (PMID 25013928, 2014). "Many studies have shown that the transcription factor of MEIS1, which is fine-tuned by calcium signaling, plays pivotal roles in the self-renewal maintenance and differentiation inhibition during leukemogenesis or other cancer development." (PMID 41392978, 2025). "Furthermore, KEGG enrichment analysis shows that the knockdown of Meis1 and Malat1 affected proteins that play a role in various cancer pathways, which is consistent with their previously reported functions in tumorigenesis." (PMID 39851553, 2025). "Interestingly, the repertoire of Meis1 regulators includes several reported miRNAs such as miR-155, miR-196b and miR-144, which were shown to downregulate Meis1 and impact hematopoiesis and cancer progression." (PMID 39851553, 2025). "MEIS1 has the potential as a cancer immunotherapy target and is worthy of more attention." (PMID 36836180, 2023). "Moreover, MEIS1 expression is related to some immune subtypes and molecular subtypes in different types of cancer." (PMID 36836180, 2023). "In most cancers, MEIS1 expression was positively related to most ICPGs expression." (PMID 36836180, 2023). "For the value of MEIS1 on the prognosis of cancer patients, it could be determined by the activity of the MEIS1 protein which depends on the environment in which the cell exists." (PMID 36836180, 2023). "KEGG analysis indicates that “Transcriptional misregulation in cancer” might play a vital role in the effect of MEIS1 on cancers." (PMID 36836180, 2023). "Therefore, the immunotherapeutic effect of cancer patients can be predicted according to MEIS1 expression." (PMID 36836180, 2023). "According to KEGG analysis in this study, “Transcriptional misregulation in cancer” might play a vital role in the effect of MEIS1 on cancers." (PMID 36836180, 2023). "Bioinformatics was used to excavate the potential mechanisms of MEIS1 across different cancers." (PMID 36836180, 2023).
cancer (continued). "In summary, we identified uniquely downregulation of the MEIS subfamily in pan-cancer, especially MEIS1 in TCGA-COAD dataset, which was validated in external GEO datasets and CRC cell lines as well as CRC samples, and discovered that impaired expression of MEIS1 harmed the survival of CRC patients." (PMID 35351858, 2022). "Meis1 and Fut8 gene, which are activated by Fli-1 and the LDB1 complex bound at their enhancer regions, encode two proteins, which have functions in different cancer." (PMID 33733070, 2021). "The latest and most efficient drugs effectively decrease the levels of MEIS1 in cancer cells." (PMID 34698191, 2021). "When MEIS inhibitors are used in cancer studies, downregulation of Hoxa9 could be beneficial because MEIS1 is known to cooperate with HOXA9 in carcinogenesis." (PMID 32409701, 2020). "On the other hand, MEIS1 has a tumor suppressor role in some cancers." (PMID 33402862, 2020). "In particular, MEIS1, FLT3, TNF, PBK, and IGF2BP, all associated with cancer, were down-regulated." (PMID 32698374, 2020). "Meis1 was first discovered in cancer as a viral integration site." (PMID 32409701, 2020). "Besides the role of MEIS1 in healthy organs, maintaining stemness state of cancer stem cells has been also discussed in various cancers." (PMID 32819319, 2020). "However, MEIS-1 can also function as a negative regulator of cancers by inhibiting cell proliferation and inducing cell cycle arrest." (PMID 29632641, 2018). "Since invasion and migration are main features of malignancies, our data reveal that MEIS1 overexpression could be a potential approach to improve the cancer prognosis of advanced metastatic ccRCC." (PMID 28270206, 2017). "It is therefore evident that Meis1 is part of a sophisticated network and controlling its expression could ultimately affect cellular proliferation or senescence, and even the pathogenesis of certain diseases like cancer and ischemic cardiomyopathy." (PMID 39851553, 2025). "So, there may be interference with HOX genes and PBX genes during the role of MEIS1 in cancers." (PMID 36836180, 2023). "Also, MEIS1 would function as a tumor suppressor in some other kinds of human cancer." (PMID 28270206, 2017). "The results showed that DNM1, MEIS1, and SUSD3 were differentially expressed between various cancers and normal tissues." (PMID 38167056, 2024). "To study the relationship between the expression levels of DNM1, MEIS1, and SUSD3 and the prognosis of 33 kinds of cancer, we carried out a survival correlation analysis." (PMID 38167056, 2024). "Several top-ranking genes, such as MEIS1, ZDHHC11, CWH43, TTC12, and CDH22, have been supported by recent studies as playing roles in various cancers and aging-related processes." (PMID 39499149, 2024). "MEIS1 expression was correlated with Macrophages_M2, CD8+T cells, Macrophages_M1, Macrophages_M0 and neutrophils in many cancers." (PMID 36836180, 2023). "Seven winning TFs (ETV4, ID2, MEIS1, NR4A3, RARA, TCF3, and ZBTB16) are related to transcriptional misregulation in cancer (p-value: 6.9 × 10−5)." (PMID 36101460, 2022). "These lines were selected based on their differential expression of HOXA9, MEIS1, and PLA2G4A in the Cancer Cell Line Repository sequencing data." (PMID 34502319, 2021). "MLL1 is frequently upregulated in cancers, resulting in increased expression levels of HOX and MEIS1 target genes, which link MLL1 with its tumorigenic properties." (PMID 34698191, 2021). "MEIS1 (Myeloid ecotropic viral integration site 1), as a homeobox (HOX) transcription factor, has a dual function in different types of cancer." (PMID 31090196, 2019). "These genes include LRAT, MEIS1, ST8SIA1 and STC2 which have all previously been shown to be subject to transcriptional downregulation as an effect of DNA hypermethylation in human cancers." (PMID 28931069, 2017). "In RA-treated human carcinoma cell line NT2/D1, a treatment that induces neuronal terminal differentiation, Meis1 is also up regulated." (PMID 26857994, 2016).
cancer (continued). "Several target genes of miR-204, including HOXA10, MEIS1, FOXC1, MAP1LC3B, BCL2, NTRK2, SOX4 and EphB2, have been identified in different cancers." (PMID 26710269, 2015). "We co-stained for Meis1-EGFP with K14, K10, and cancer stem cell markers such as β4 integrin, CD34, and K15." (PMID 25013928, 2014). "Mice with epidermal deletion of Meis1 developed significantly fewer DMBA/TPA-induced benign and malignant tumors compared with wild-type mice, suggesting that Meis1 plays a role in both tumor development and malignant progression." (PMID 25013928, 2014). "MiR-196b-5p is dysregulated in many malignancies, has been related to cancer prognosis, and targets c-myc, ERG, MEIS1, FAS, ABL1, BCL-2 and several HOX genes." (PMID 25329796, 2014). "Initially, we only performed a series of bioinformatics analysis of MEIS1 in multiple databases, the mechanisms of MEIS1 in different cancer types were not verified." (PMID 36836180, 2023). "MEIS1 expression was different in various immune subtypes including C2 (IFN-gamma dominant), C5 (immunologically quiet), C3 (inflammatory), C4 (lymphocyte depleted), C6 (TGF-b dominant) and C1 (wound healing) in various cancers." (PMID 36836180, 2023). "The expression of MEIS1 was correlated with macrophages_M2 in 20 cancer types, CD8+T cells in 19 cancer types, Macrophages_M1 in 15 cancer types, macrophages_M0 in 13 cancer types and neutrophils in 10 cancer types." (PMID 36836180, 2023). "Moreover, MEIS1 was a directly repressed target of MYC, and via effects on HOXB13, links MYC activity to androgen receptor activity to mediate cancer development." (PMID 36836180, 2023). "Furthermore, methylation patterns in SDMCs influenced the transcription of several genes (MEIS1, MIA3, PCDHAC2, SH3BP4, and ATP8B1) involved in well-known cancer-related pathways and cancer hallmarks (FDR < 0.05)." (PMID 36348462, 2022). "Notably, six genes—MLLT3, MEIS1, PBX1, PBX3, HOXA10, KMT2A—were found to play a role in transcriptional dysregulation in cancer." (PMID 35743243, 2022). "In other cancers, the expression of Meis1 was either reduced or did not lead to a significant change." (PMID 33402862, 2020). "Moreover, the correlation between MEIS1 and CSC marker SOX2 has been shown in ESCC predicting cancer stemness properties for MEIS1 in the disease." (PMID 32819319, 2020). "The connection between hth, tsh and nuclear receptors might extend beyond Drosophila, as we found a significant co-overexpression of the human homologues of hth, tsh and ftz-f1, the MEIS1, TSHZ and NRA52 genes, in specific cancer cell lines and tumors." (PMID 28687780, 2017). "The constructed TF and miRNA regulatory networks showed that hub nodes including miR-126-3p, miR-30c-2-3p, HOXA5, MEIS1 and TBX5 were markedly different in two separate TF and miRNA enrichment analyses, and their levels were significantly decreased in cancer tissues." (PMID 26035298, 2015). "In this work, MEIS1 overexpression could repress in vitro invasion and migration of high aggressive ccRCC cell line Caki-1 and lead to decreased EMT, the critical step mediating cancer metastasis." (PMID 28270206, 2017). "To determine whether or not the observed increase of Meis1 expression is associated with the development of increased mesenchymal tissue owing to EMT, we analyzed carcinomas in which the expansion of mesenchymal tissue is known to occur." (PMID 25013928, 2014). "Therefore, to look for independent evidence of MEIS1 function within ABCB1 context, we turned to our recently published database of drug sensitivity for a panel of cancer cell lines and the publicly available Broad Institute Cancer Cell Line Encyclopedia (CCLE) microarray database." (PMID 23442791, 2013). "HOXD8 has never been reported to be involved in cancer initiation before, so this is the first report of cooperation between HOXD8 and MEIS1 in AML induction." (PMID 26606454, 2015).
cancer (continued). "Using PPI analysis, the critical pathway of functional genes was found involved in the hematopoietic cell lineage and transcriptional misregulation in cancer, including HOXA10, MEIS1, FLT3, CD14, PROM1, RUNX2, and RUNX1 (data not shown), indicating the dominant roles of HOXA and MEIS1 in MLL-R ALL." (PMID 36276286, 2022). "Other MS loci display marked cancer-type specificity, for example, MSI events within the 5′ UTR region of ZNF738, C10orf140, ZNF271 and RAB28 are specific to COAD tumours, whereas those in EBP, TMEM182, MIR567 and MEIS1 are absent or substantially depleted in STAD compared to COAD and UCEC tumours." (PMID 28585546, 2017).